RNU7-113P (RNA, U7 small nuclear 113 pseudogene)
Gene: Small nuclear RNA gene on chromosome 2 (20,246,326 to 20,246,387, reverse strand). Ensembl gene ENSG00000238735.
Homologues: Orthologues: chimpanzee U7 (85% identical), macaque U7 (76% identical). Paralogues in human: RNU7-13P (85% identical), RNU7-167P (85% identical), RNU7-124P (84% identical), RNU7-7P (84% identical), RNU7-81P (84% identical), RNU7-10P (82% identical), RNU7-148P (82% identical), RNU7-18P (82% identical), RNU7-28P (82% identical), RNU7-35P (82% identical), RNU7-45P (82% identical), RNU7-48P (82% identical), and 141 more.